DPP4 (dipeptidyl peptidase 4)
Diseases named in the same sentence as DPP4 in open-access papers (continued):
Sharing a sentence is not in itself a finding about the gene and the disease.
Hyperglycemia (continued). "Previous results indicated that chronic exposure to hyperglycemia stimulates DPP4 expression and activity, but these results were obtained in subjects with >8.5% HbA1c." (PMID 29958403, 2018). "Another enzyme that can be targeted to minimize post-prandial hyperglycemia is dipeptidyl peptidase-4 (DPP-4) which is serine protease." (PMID 30542284, 2018). "Long-term treatment of HBK001 in KKAy mice can ameliorate hyperglycemia as well as improve glucose tolerance, while linagliptin fails to achieve such glucose-lowing effects despite inhibiting 95% of serum DPP4 activity." (PMID 28659588, 2017). "DPP-4 inhibitors control hyperglycemia by blocking DPP-4 enzyme, which degrade incretin hormones-glucose-dependent insulinotropic polypeptide (GIP) and glucagon-like peptide-18." (PMID 29150631, 2017). "Previous reports verified that incretin agents including DPP-4 inhibitors exert renal protective effects in vitro and in vivo against increased renal oxidative stress under hyperglycemia." (PMID 28725273, 2017). "The DPP-4 inhibitors are incretin-related drugs that improve hyperglycemia in a glucose-dependent manner and have been reported to exert favorable effects on atherosclerosis." (PMID 27711199, 2016). "In the second study, the incretin-based antihyperglycaemic agents liraglutide (a GLP-1 agonist) and vildagliptin (a dipeptidyl peptidase 4 [DPP-4] inhibitor) were shown to effectively ameliorate hyperglycaemia when co-administered with pasireotide." (PMID 26906713, 2016). "Although DPP-4 inhibitors were developed to control hyperglycemia, it is now established that these inhibitors have effects beyond glycemic regulation." (PMID 27391040, 2016). "This is especially relevant when dealing with patients that are treated with DPP4 inhibitors or that have aberrant DPP4 activities, for example due to hyperglycemia or hypoxia." (PMID 26544044, 2015). "The use of DPP-4 inhibitors for the treatment of hyperglycemia and NODAT in kidney transplant recipients is gaining more interest." (PMID 24817885, 2014). "Treatment with the GLP-1 analog liraglutide or the dipeptidyl peptidase 4 (DPP-4) inhibitor vildagliptin was most effective in countering hyperglycemia in this population, while metformin and nateglinide had little effect." (PMID 23673515, 2013). "The modulation of DPP4 activity in endothelial cells is site specific; in fact hyperglycemia is able to increase in a significant manner the DPP4 activity only in microvascular endothelial cells." (PMID 23853775, 2013). "Selection of a DPP-4 inhibitor that effectively suppresses postprandial hyperglycemia contributes to the maintenance of ideal HbA1c levels." (PMID 22867630, 2012). "Further studies are needed to determine which other drugs would act in concert with DPP-4 inhibitors to effectively control postprandial hyperglycemia." (PMID 22189184, 2011). "The α-glucosidase inhibitors and the dipeptidyl peptidase-4 (DPP-4) inhibitors have been found to effectively decrease postprandial hyperglycemia independently." (PMID 22189184, 2011). "Metformin and dipeptidyl peptidase 4 (DPP4) inhibitors have been effective in some individuals; however, the hyperglycemia can be intractable thus requiring insulin to achieve glycemic control." (PMID 22043170, 2011). "DPP-4 inhibitors are only effective under conditions of hyperglycaemia and disappear when blood glucose values fall below the normal range." (PMID 21756359, 2011). "These include studies demonstrating the effectiveness of dipeptidyl peptidase-4 (DPP-4) inhibitors in patients with renal disease and reports showing improvements in postprandial hyperglycemia with nateglinide and/or acarbose in patients with rheumatoid arthritis or collagen diseases." (PMID 41464548, 2025). "The cause-and-effect relationship between hyperglycemia and increased DPP4 activity is still not established." (PMID 39507187, 2024).
Hyperglycemia (continued). "Following this, hyperglycemia could stimulate DPP4 mRNA expression and enzyme activity in human glomerular endothelial cells." (PMID 39205219, 2024). "Incretin-based therapies (eg dipeptidyl peptidase 4 [DPP-4] inhibitors [eg vildagliptin] and GLP-1 receptor agonists [eg liraglutide]) have also been shown to be an effective treatment option in managing pasireotide-associated hyperglycemia." (PMID 38577574, 2024). "Because key pathophysiological changes in hyperglycemia include chronic low-grade inflammation, it could be hypothesized that DPP4 activity may play an essential role in promoting hyperglycemia through its pro-inflammatory actions." (PMID 39507187, 2024). "DPP4 is a well-characterized gene which regulates peptide hormones and regulates the endocrine pathway, and when inhibited enhances postprandial metabolism and can be used to treat hyperglycemia." (PMID 38288350, 2023). "Since DPP4 can regulate the level of blood glucose through its enzymatic function and hyperglycemia is a risk factor for atherosclerotic disease, we assessed the contribution of hematopoietic and nonhematopoietic cell derived DPP4 to glucose metabolism." (PMID 36683148, 2023). "This receptor and dipeptidyl peptidase 4 (DPP4), which may be a factor in the severity of COVID-19 infection, are present in several physiological processes and are modulated by hyperglycemia and pharmacological therapies that are common in DM patients." (PMID 37260447, 2023). "Similarly, some evidence implies that individuals taking the AMPK agonist metformin or of the dipeptidyl peptidase-IV (DPP4) inhibitor sitagliptin, both drugs widely used to treat hyperglycemia, have a lower risk of PCa." (PMID 36359354, 2022). "Indeed, the loss of effect of diet-induced hyperglycaemia on C-peptide secretion in Dpp4 KO mice together with lack of Dpp4 association with C-peptide levels in prediabetes suggests that hyperglycaemia may override the Dpp4 genetic control independently of the incretin effect." (PMID 35190847, 2022). "One question that arises is whether hyperglycemia can impact the glycosylation of DPP4, modifying its activity and dimerization." (PMID 36009573, 2022). "We used a mouse model under HCD to mimic prediabetes and determine whether hyperglycaemia affects Dpp4 expression." (PMID 35190847, 2022). "Therefore, it is highly likely that the gut-restricted GPR40 agonist has the potential to be more efficacious than DPP4 inhibitor to control hyperglycemia in T2D patients, in addition to body weight reduction." (PMID 36386134, 2022). "Anagliptin is a novel dipeptidyl peptidase-4 (DPP-4) inhibitor for the treatment of hyperglycemia." (PMID 34288819, 2021). "Chronic hyperglycemia may lead to the activation of DPP4, and long-term exposure to high glucose levels may lead to endothelial damage with a consequent increase in DPP4 secretion." (PMID 33312197, 2020). "Dipeptidyl peptidase-4 (DPP-4) inhibitors have been known to improve hyperglycemia in T2D patients by stimulating the incretin effects via suppressing the degradation of incretins, such as glucagon-like peptide-1 (GLP-1) and glucose-dependent insulinotropic polypeptide (GIP)." (PMID 32646003, 2020). "Thus, long-term Teneligliptin treatment reduced DPP-4 levels and activity in HUVECs exposed to chronic hyperglycemia." (PMID 29507662, 2018). "Additionally, hyperglycemia was reduced in these diabetic rats by sitagliptin treatment at an effective dose to inhibit dipeptidyl peptidase-4 (DPP-4)." (PMID 29084156, 2017). "DPP4 inhibitors have now been wildly used as antidiabetic drugs at clinical practice, moreover, protective effects of DPP4 inhibitors on cognitive impairment have also been reported in a retrospective longitudinal study in patients with hyperglycemia." (PMID 28798686, 2017). "Dipeptidyl peptidase-4 (DPP-4) inhibitors are a novel class of drugs used to treat hyperglycaemia." (PMID 26811539, 2016).
Hyperglycemia (continued). "It has been reported that the manipulation of glucagon by receptor agonists, such as glucagon-like peptide-1 (GLP-1), or by dipeptidyl peptidase-4 (DPP-4) inhibitors can decrease glucagon levels and eventually reduce the degree of hyperglycemia and its associated risks." (PMID 27092078, 2016). "DPP-4 inhibitors mainly target postprandial hyperglycemia and glucose fluctuations." (PMID 25995772, 2015). "Dipeptidyl peptidase-4 inhibitor (DPP-4i) attenuates postprandial hyperglycemia (PPH) and may have cardio-protective effects." (PMID 26084668, 2015). "Microcirculation is the site of tissue nutrition, of gas exchange, and also of removal of cellular excreta and, although DPP4 is present in all vascular beds, hyperglycemia is able to increase the DPP4 activity only from the endothelial cells at the microvascular compartment." (PMID 26146634, 2015). "Such difference might be attributed to the subjects in our study having relatively mild hyperglycemia and lower BMIs, as well as, maybe Orientals are more sensitive to DPP-4 inhibitors." (PMID 24917890, 2014). "Furthermore, augmented levels of GLP-1, mediated by the inhibition of DPP-4, exert anti-inflammatory actions in hyperglycemia, which may mitigate DN." (PMID 37047505, 2023). "Thus, we investigated whether inhibiting DPP-4 affects tau pathology and cognition in a mouse model of tauopathy with hyperglycemia." (PMID 31126115, 2019). "Dipeptidyl peptidase 4 (DPP4) is produced and secreted by many cell types including endothelium, smooth muscle, immune cells and fat cells, and triggered by hyperglycemia and hypoxia." (PMID 40514620, 2025). "T2DM still has potential through chronic hyperglycemia, oxidative stress, and advanced glycation end products (AGEs) to disrupt the physiological interaction between PYY and DPP-4; thus, further human studies should address this question." (PMID 40142315, 2025). "DPP4 inhibitors, oral antidiabetic drugs approved by the FDA as early as 2006, have provided promising results for hyperglycemia." (PMID 41214779, 2025). "Specifically, dipeptidyl peptidase-4 (DPP-4) is an enzyme that is involved in the inhibition of the rapid degradation of hormones, which prevents hyperglycaemia." (PMID 39682687, 2024). "Taking into account the pathogenesis of post-steroid-induced hyperglycemia, the initiation of therapy with glucagon-like peptide 1 (GLP-1) analogs and dipeptidyl peptidase 4 (DPP-4) inhibitors should be considered." (PMID 39407860, 2024). "Combination therapy with DPP4 and SGLT2 inhibitors has been suggested as an effective therapy that maintains additive efficacy in improving hyperglycemia while retaining the safety profile of each medication." (PMID 39114607, 2024). "Several treatments for hyperglycemia, including SGLT-2 inhibitors, metformin, calorie restriction, and bariatric surgery, can reduce circulating DPP-4 levels." (PMID 38476668, 2024). "Sitagliptin, a dipeptidyl peptidase 4 (DPP4) inhibitor, was administered at a dose of 25 mg to treat hyperglycemia, and the HbA1c level subsequently decreased to 6.1%." (PMID 39135967, 2024). "Several new classes of medications have been developed for the treatment of hyperglycemia, including glucagon-like peptide I (GLP-I) analogs, sodium-glucose co-transporter 2 (SGLT-2) inhibitors, and dipeptidyl peptidase 4 (DPP-4) inhibitors." (PMID 37893048, 2023). "Dipeptidyl peptidase 4 inhibitors and GLP-1 receptor agonists can be effective in reducing hyperglycemia, being considered in stage II of the treatment." (PMID 37628857, 2023). "Sitagliptininhibits DPP-4, leading to stabilization of the short-lived incretin peptides GLP-1 and GIP.The use of DPP-4 inhibitors in managing hyperglycemia in adults with T2D varies based onlocal practice guidelines." (PMID 37498865, 2023). "Several methods are used by dipeptidyl peptidase-4 (DPP4) inhibitors and glucagon-like peptide-1 (GLP-1) analogs to lower hyperglycemia." (PMID 37187644, 2023).
Hyperglycemia (continued). "The alkaloids have been reported to regulate hyperglycemia via α-glucosidase and α-amylase inhibition, sensitizing insulin production, inhibition of PTP-1B and DPP-4 pathways, and managing oxidative stress condition." (PMID 37138848, 2023). "Combined treatment of DPP4 inhibitor, GPR40 agonist, and SSTR5 antagonist dramatically increased plasma insulin and suppressed hyperglycemia in db/db mice." (PMID 36386134, 2022). "Although many therapeutics have been deployed to combat hyperglycemia, few of them directly target β-cell pathogenesis besides of GLP-1 analogs, such as liraglutide, and dipeptidyl peptidase-4 (DPP-4) inhibitors, such as sitagliptin." (PMID 35308210, 2022). "Activation of GLP-1 signaling by in vivo administration of GLP-1, GLP-1 analogs resistant to DPP-4, or DPP-4 inhibitors can ameliorate hyperglycemia in murine models and stimulate ⍺-cell proliferation, as well as ⍺- to β-cell transdifferentiation." (PMID 33921851, 2021). "Therefore, it remains unclear whether DPP-4 inhibitors slow the process of atherosclerosis directly via the improvement of hyperglycemia and related AGE formation, indirectly via the amelioration of comorbid risk factors, or through the pleiotropic effects of incretins." (PMID 32646003, 2020). "Specifically, increases in circulating DPP4 would lead to a decrease in GLP-1, leading to reduced insulin and increased glucagon secretion, resulting in hyperglycemia." (PMID 31911667, 2020). "Cleavage of His-Ala from the N-terminus of GLP-1 by DPP4 inactivates GLP-1 and its effect on insulin release stimulation and its inhibition of the release of glucagon, resulting in hyperglycemia." (PMID 30972338, 2019). "Dipeptidyl peptidase-4 (DPP-4) inhibitors and sodium–glucose co-transporter 2 (SGLT2) inhibitors improve hyperglycemia, and the usefulness of co-administration of DPP-4 inhibitors and insulin therapy has been well established." (PMID 28725273, 2017). "DPP-4 inhibitor is a new class of oral antidiabetic drugs which, by inhibiting the degradation of GLP-1 and GIP, improves fasting and postprandial hyperglycemia." (PMID 25140306, 2014). "A variety of pharmaceutical options for reduction of hyperglycemia are available, including metformin, sulfonylureas and incretin-based therapies (GLP-1 analogs and DPP-4 inhibitors)." (PMID 23570327, 2013). "Native GLP-1 has been shown to reduce hyperglycaemia in T2D; however, as GLP-1 is rapidly (within 2–3 minutes) degraded by the enzyme dipeptidyl peptidase-4 (DPP-4), continuous GLP-1 infusion would be required to maintain optimal glycaemic control." (PMID 24011363, 2013). "Thus, DPP-4 inhibition addresses one defect that may contribute to hyperglycemia in this disease." (PMID 23554750, 2012). "Advances in the treatment of hyperglycaemia include glucagon-like peptide-1 (GLP-1) receptor agonists, such as exenatide and liraglutide, and dipeptidyl peptidase-4 (DPP-4) inhibitors, such as sitagliptin and saxagliptin." (PMID 21615670, 2011). "DPP-4 inhibitors, such as sitagliptin, increase active GLP-1 and GIP levels by inhibiting DPP-4 enzymatic activity and improve hyperglycemia in a glucose-dependent fashion by increasing serum insulin and decreasing serum glucagon levels in diabetic patients." (PMID 22189184, 2011). "Osteoclasts are also involved in influencing systemic metabolism through secreted factors, such as dipeptidylpeptidase-4 (DPP4), which reduces GLP-1 levels, leading to decreased insulin, increased glucagon secretion, and hyperglycemia, linking bone remodeling to energy homeostasis." (PMID 41559024, 2026). "The absence of marked hyperglycemia suggests a euglycemic variant of DKA, often associated with factors such as DPP-4 inhibitor use and extensive head trauma as in this case." (PMID 40725973, 2025). "As DPP-4 inhibitors appear to be ineffective in pasireotide-induced hyperglycemia due to their mechanism of action, we decided not to include them in our algorithms." (PMID 39735646, 2024).
Hyperglycemia (continued). "AGSIs have been regarded as the most eminent hyperglycemia controlling agents along with other medications such as glucagon-like peptide 1 (GLP-1) receptor agonists, dipeptidyl peptidase-4 (DPP-4) inhibitors, and sodium-glucose cotransporter-2 (SGL-2) inhibitors." (PMID 37175232, 2023). "It has been reported that the anti-diabetic drug dipeptidyl peptidase 4 inhibitor vildagliptin reduced the expression of DRP1 and Fis1, blocked the movement of DRP1 to the mitochondria, and slowed mitochondrial fragmentation induced by hyperglycemia." (PMID 37760030, 2023). "Surprisingly, the glucose challenge failed to significantly reduce liver Dpp4 expression, as observed in normoglycaemic mice, suggesting that the hepatic sensing of oral glucose is abrogated in hyperglycaemia." (PMID 35190847, 2022). "With specific attention to alogliptin as a DPP-4 inhibitor, the U.S. Food and Drug Administration (FDA) approved three new oral alogliptin-based agents in hyperglycemia treatment, including alogliptin alone, alogliptin-metformin hydrochloride combination, and alogliptin-pioglitazone combination." (PMID 36145615, 2022). "In the present study, we used an animal model of progressive renal fibrosis without hyperglycemia to elucidate the effects of DPP-4 inhibition independent of GLP-1." (PMID 33803842, 2021). "Secondly, linagliptin fails to ameliorate hyperglycemia in diabetic KKAy mice despite the fact that serum DPP4 was over 95% inhibited, while HBK001 can effectively regulate glycemic control although DPP4 inhibition is only up to 50%." (PMID 28659588, 2017). "Although no specific recommendations regarding pasireotide-induced hyperglycemia in patients with acromegaly have been published, treatment with metformin plus a DPP-4 inhibitor, GLP-1 agonist, or insulin would most likely have similar efficacy." (PMID 27405306, 2016). "After the manifestation of severe hyperglycemia in the db/db mice fed an SL or SO diet, treatment with the DPP-4 inhibitor was no longer capable of reducing the blood glucose levels." (PMID 26937254, 2016). "In a previous study in ZDF rats, chronic treatment with a different DPP4-inhibitor (FE 999011; 10 mg/kg per os, twice a day) delayed, but did not prevent, the onset of hyperglycemia." (PMID 23071636, 2012). "The absence of hyperglycemia in EuDKA can complicate diagnosis, emphasizing the importance of careful monitoring and consideration of this condition, especially in trauma patients using medications like DPP-4 inhibitors." (PMID 40725973, 2025). "Moreover, increased DPP4 activity enhances the degradation of GLP-1 and lipid accumulation, and these factors may also contribute to the development of hyperglycemia leading to DM." (PMID 39507187, 2024). "In addition, DPP4, which inactivates GLP-1, is an important therapeutic target for hyperglycemia." (PMID 35655996, 2022). "Researchers reported that DPP4 is responsible for degradation of B-type natriuretic peptide (BNP), stromal cell–derived factor 1α (SDF-1α), and substance P. Gliptins effectively mitigate the deleterious effects of postprandial hyperglycemia on oxidative stress, inflammation, and CV remodeling." (PMID 35945358, 2022). "Given the unique binding profile of pasireotide and experience from studies in healthy volunteers, incretin-based therapies (dipeptidyl peptidase 4 [DPP-4] inhibitors and glucagon-like peptide 1 [GLP-1] receptor agonists) may be useful for managing hyperglycemia during pasireotide treatment." (PMID 34275099, 2021). "Saxagliptin, a relatively new dipeptidyl peptidase-4 (DPP-4) inhibitor, was approved by the US Food and Drug Administration (FDA) in July 2009 and the European Medicines Agency in October 2009 to be used with diet and exercise to control hyperglycemia in adults with T2DM." (PMID 25889498, 2015).